NHERF1 (NHERF family PDZ scaffold protein 1)
Diseases named in the same sentence as NHERF1 in open-access papers (continued):
Sharing a sentence is not in itself a finding about the gene and the disease.
tumor (continued). "Tumours formed from T47D/NHERF-786 (72.4 ± 13.9 mg, n = 10) were significantly larger than those from T47D/Babe cells (37.7 ± 8.8 mg, n = 8) (P = 0.043), suggesting that lowered NHERF1 expression promotes tumour growth in vivo." (PMID 17078868, 2006). "The study presented here recapitulated the putative tumour suppressor activity of NHERF1 in a cell culture model." (PMID 17078868, 2006). "Based on our published genetic evidence implicating NHERF1 as a tumour suppressor gene, we propose that one of the functional activities responsible for its tumour suppressor role is proliferative suppression of mammary epithelial cells." (PMID 17078868, 2006). "Coupled with our genetic evidence reported earlier, the current functional analyses substantiate NHERF1 as a tumour suppressor gene in mammary gland." (PMID 17078868, 2006). "NHERF1 knockdown T47D cells implanted at mammary fat pads of athymic mice formed larger tumours than did control cells." (PMID 17078868, 2006). "Indeed, NHERF1 displays anti-tumor properties when it is located underneath the plasma membrane; on the contrary, it acts as an oncogene when localized in the cytoplasm or in the nucleus." (PMID 35223518, 2022). "As it is upregulated in tumor tissues compared to normal samples, NHERF1 could represent a potential target for clinical applications." (PMID 35223518, 2022). "Indeed, NHERF1 enacts its tumor suppressive program through the binding of EGFR and inhibition of EGFR-mediated signaling." (PMID 35223518, 2022). "A recent study involving 26 cases of NSCLC tumor puncture and 18 cases of matched tissue sections showed that the increase and mislocation of NHERF1 from immunohistochemistry could be used to indicate cancer invasion." (PMID 32164629, 2020). "From previous studies in NSCLC, NHERF1 proteins in the plasma were increased in patients, suggesting NHERF1 might be useful for the evaluating tumor development and progression." (PMID 32164629, 2020). "NHERF1 expression was detected in the apical membrane, cytoplasm, and nucleus of tumor cells." (PMID 31540486, 2019). "This tumor also showed only focal NHERF1 dot-like expression." (PMID 29983887, 2018). "Whereas the NHERF1 membranous staining might suggest the presence of membrane microvilli in these tumor cells, this assumption needs to be confirmed by ultrastructural studies." (PMID 29983887, 2018). "NHERF1 expression was detected in the apical membrane, cytoplasm, and nucleus of tumor samples." (PMID 29716631, 2018). "Finally, we believe that our intriguingly results warrant additional studies aimed to evaluate tumor microenvironment regulation in combination with NHERF1 as a possible targeted-oriented therapeutic approach." (PMID 29716631, 2018). "The lack of nuclear NHERF1 was noticeably associated to tumor size > 2 cm (p = 0.014), while its presence was linked to MIB1 negative expression (p < 0.001)." (PMID 29716631, 2018). "Regarding CRC, a recent study stated the tumor suppressor activity of NHERF1." (PMID 29551770, 2018). "NHERF1 transcripts demonstrated a higher level in tumors (p = 0.0083, Tumor vs Normal)." (PMID 27999191, 2017). "Moreover, in the same Group 1, where TWIST1 was overexpressed in the tumor site, we noted also a positive correlation between nuclear NHERF1 and TWIST1." (PMID 29152120, 2017). "Furthermore, in the tumor compartment of the Group 1, we detected a positive correlation between nuclear NHERF1 and cytoplasmic β-catenin." (PMID 29152120, 2017). "NHERF1 may behave either as a tumor suppressor when it is localized at the plasma membrane, or as an oncogenic protein when it is shifted to the cytoplasm or nucleus." (PMID 29029467, 2017). "We could speculate that, also in the tumor, the physiologic role of NHERF1 was required to support β-catenin localization at the cell-cell junction." (PMID 27765918, 2016). "Moreover, tumor samples showed a higher cytoplasmic NHERF1 expression than the tumor-adjacent normal tissues." (PMID 27765918, 2016).
tumor (continued). "Finally, tumours overexpressing cytoplasmic NHERF1 showed a significant trend with positive EGFR status (P = 0.053)." (PMID 23991686, 2013). "In the cells of all tumour samples, a variable cytoplasmic NHERF1 expression was detected." (PMID 23991686, 2013). "The strong correlation with poor vascularization and the hypoxia-inducible factor-1α (HIF-1α), a marker of hypoxic tumors, indicates that NHERF1 expression might play an important role in driving metastatic progression by modifying the tumor microenvironment." (PMID 22439624, 2012). "However, a significant high proportion of grade 3 tumors showed the same PVI+/membranous NHERF1- expression phenotype, highlighting that grade 2 tumor subgroup with poor prognosis is regarded as being similar to grade 3 cancers." (PMID 22439624, 2012). "Our study was conducted on a tissue type most relevant to NHERF1 tumour suppressor activity." (PMID 17078868, 2006). "Whether the negative regulation of growth factor signaling by NHERF1 is responsible for the NHERF1 tumour suppressor function in mammary gland remains to be determined." (PMID 17078868, 2006). "The tumourigenic mutations of NHERF1 partially or completely disrupt the binding of SYK or merlin, both of which are tumour suppressors, suggesting that NHERF1 converges in a pathway mediated by the two tumour suppressors." (PMID 17078868, 2006). "Our study affirmed the tumour suppressor activity of NHERF1 in breast which may be related to its regulatory effect on cell cycle." (PMID 17078868, 2006). "However, a recent in vivo study provided strong genetic support for NHERF1 as a tumor suppressor." (PMID 31002735, 2019). "Whether NHERF1 is a tumor suppressor or an oncogene has been debated in the literature." (PMID 31002735, 2019). "Analyzing NHERF1 reactivity at membrane level, its absence was observed in IDCs (p = 0.002) and positive lymph node status (p = 0.013); conversely mNHERF1 expression was significantly associated with tumor size ≤2 cm (p = 0.039) and MIB1 negative (p = 0.019)." (PMID 29716631, 2018). "This up-regulation of NHERF1 was rapid for hypoxia (within 30 min) suggesting that NHERF1 could serve as a rapid response element to the tumor hypoxia microenvironment and might contribute to the regulation to the VEGF/VEGFR signaling pathway in driving metastatic progression." (PMID 27999191, 2017). "Ezrin and NHERF-1/2 are adaptor proteins that have diverse binding partners and facilitate the interaction of PODXL with the cytoskeletons of tumor cells." (PMID 38203331, 2023). "In detail, the interaction between NHERF1 and ACTN4 increased ACTN4 ubiquitination and degradation by the proteasome, impacting actin cytoskeleton organization and tumor cell migration and invasion." (PMID 35223518, 2022). "YAP also interacts with adaptor molecule NHERF1/EBP50, an in vivo tumor repressor for intestinal adenoma development and an organizer of polarity structures such as ependymal cilia." (PMID 34944845, 2021). "In this study, we examined the expression and sub-localization of β-catenin, NHERF1 and RASSF1A proteins, in addition to the methylation status of RASSF1A, in tumor adjacent normal tissue, primary tumors, and paired liver metastases of metastatic CRC." (PMID 27765918, 2016). "Recently, we have suggested that nuclear NHERF1 could be a potential new marker, representing an early indicator of pre-morphological triggering of CRC carcinogenesis and demonstrating an association with the hypoxic tumour microenvironment in nodal and liver metastases." (PMID 23991686, 2013). "Tumour cells disseminated in the stroma and, frequently, very close to blood vessels within the tumour microenvironment, overexpressed PAR-2 and NHERF1, showing a wide co-localization of the two proteins in the cytoplasm compartment." (PMID 23991686, 2013).
tumor (continued). "PODXL regulates epithelial and tumor cell motility through interactions with the actin polymerization complexes, including the ERM (ezrin–radixin–moesin) family and PDZ protein Na+/H+ exchanger regulatory factors 1 and 2 (NHERF-1/2)." (PMID 38203331, 2023). "MINDIN-dependent downregulation of NHERF-1 promoted tumor cell migration and proliferation without affecting osteomimicry and adhesion." (PMID 33498862, 2021). "Although NHERF1 is generally consensed as a gene with tumor suppressor functions, it is not quite understood why it often upregulated in malignant cancer cells." (PMID 32164629, 2020). "The lack of co-localization of TCF1 and NHERF1 is not surprising because they act in different cellular compartments during the tumor progression." (PMID 31336689, 2019). "Remarkably, in the tumor area, a neo-vascular formation with a “mosaic” structure was observed with a double staining of CD34 and NHERF1, which could indicate a probable tumor cell recruitment in neo blood vessels formation with endothelial cells." (PMID 29716631, 2018). "The mechanism of action of NHERF1 in tumor cells has not been elucidated, but it has been reported that NHERF1 plays an important role in cancer development." (PMID 28430808, 2017). "The presence of identical NHERF1-labeled microlumens in clusters of normal ependymal cells that do not line the ventricular system raises the possibility of tumor initiation from these clusters." (PMID 25775275, 2015). "Moreover, we examined protein expression of NHERF1 and its relationship with PAR-2, with the aim to investigate their supposed usefulness as tumour markers in CRC." (PMID 23991686, 2013). "Moreover, we showed both a positive linear correlation between cytoplasmic NHERF1 and PAR-2 and a significant co-expression of the two proteins mostly in the margin of the tumour mass." (PMID 23991686, 2013). "Tumors overexpressing NHERF1 and VEGFR1 revealed an association with poor outcome, being characterized by an increasing tumor grade, and negative status of steroid hormone receptors." (PMID 22439624, 2012). "Tumors positive for both cytoplasmic NHERF1 and VEGFR1 expressions, compared to those with negative expressions, resulted significantly associated with tumor grade 3 (p = 0.006), negative ER (p = 0.045) and PR status (p = 0.000) (data not shown)." (PMID 22439624, 2012). "The physical and functional relation between NHERF1 and PTEN indicates they may exist in a common tumor suppressor pathway, which would predict segregation between NHERF1 and PTEN (or PI3KCA) alterations." (PMID 18190691, 2008). "Although the hypothesis contrasts with the cooperative effect of NHERF1 on PDGF signaling as suggested by some earlier studies, this mechanism is consistent with the tumour suppressor activity presented in this study." (PMID 17078868, 2006). "Among the multiple biologic pathways in which NHERF1 is involved, the signaling event that is most relevant to NHERF1 pathobiology in mammary gland is not known, nor is it certain that NHERF1 elicits tumour suppressor activity in breast." (PMID 17078868, 2006). "The adaptor protein NHERF1 shows a physiological localization at the plasma membrane, but during breast cancerogenesis progressively loses its apical localization becoming mostly cytoplasmic in no longer polarized tumor cells." (PMID 22439624, 2012). "The association analyses between NHERF1 and the other markers revealed a positive direct relation between cNHERF1 and FZD4, LRP5, LRP6, and TCF1 expression, but not with β-catenin, suggesting a possible novel tumor progression mechanism, that involves Wnt signaling components." (PMID 31336689, 2019). "However, the putative NHERF1 tumour suppressor activity has not been functionally verified." (PMID 17078868, 2006). "The negative feedback of NHERF1 to VEGF signaling pathway was disrupted, which could contribute to tumor progression, resulting in acquired resistance to anti-VEGF/VEGFR drugs." (PMID 27999191, 2017).
tumor (continued). "The complete lack of NHERF1 expression, either by shRNA knockdown in CRC cells or by gene knockout (NHERF1−/−) in ApcMin/+ mutant mice that develop multiple intestinal adenomas, was reported to increase tumor growth and the transactivating effects of β-catenin." (PMID 29551770, 2018).
cancer (50 papers, 2008 to 2025). A tumor composed of atypical neoplastic, often pleomorphic cells that invade other tissues. "Cytoplasmic NHERF1 was detected higher in primary cancer than in adjacent normal mucosa, and implicated nodal and distant metastases or lymphovascular invasion (LVI)." (PMID 32164629, 2020). "NHERF1 is extensively expressed in the epithelium of tissues and has been found to be implicated in various types of cancer." (PMID 29867145, 2018). "Taken together, these data suggested that the cancer-derived NHERF1 mutation Y24S abolished the inhibitory effect of NHERF1 on FBS-induced AKT and ERK activation." (PMID 27097111, 2016). "The further loss of NHERF1 from the apical plasma membrane in carcinoma with either detectable or undetectable cytoplasmic expression is compatible with loss of cell polarity, disorganized compact growth, and a more advanced stage of transformation." (PMID 27229317, 2016). "Identification of NHERF1 as a highly conserved E6 degradation target could inform therapies directed against both low-risk HPVs and cancer-inducing high-risk HPVs." (PMID 31002735, 2019). "Also, cytoplasmic NHERF1 was higher in primary cancer than in adjacent normal mucosa, and tumors overexpressing NHERF1 were associated with nodal and distant metastases, poor grade and lymphovascular invasion (LVI)." (PMID 27999191, 2017). "Importantly, NHERF1 loss or displacement from the plasma membrane has been reported in aggressive tumors, including carcinomas and glioblastoma." (PMID 27229317, 2016). "Given the numerous interaction partners of NHERF1/2 scaffolding proteins and their role in various signaling pathways it is not surprising that NHERF proteins have been implicated in various cancers." (PMID 37087524, 2023). "The Na+/H+ exchanger regulatory factor 1 (NHERF1) is a scaffold protein that contains modular protein-interaction domains able to interact with molecules with an impact on carcinogenesis and cancer progression." (PMID 35223518, 2022). "Further studies using gynecological models should be designed to demonstrate a defined clinical effect of NHERF1 anti-cancer agents." (PMID 35223518, 2022). "In fact, previous studies have associated NHERF-1 loss of physiological apical membrane distribution to cytoplasmic expression with EMT and increased cell migration and invasion in other types of cancer." (PMID 33498862, 2021). "NHERF1 was suggested to play an essential role in cancer initiation, development, progression and metastasis." (PMID 32164629, 2020). "In polarized colorectal epithelia, NHERF1 distributed at the apical luminal, but disrupted in cancer cases." (PMID 32164629, 2020). "We postulated that the ALK activation induced NHERF1 tended to be selectively transported into the nuclei, and such mislocalized NHERF1 proteins were likely abolished the normal functions to suppress the growth and survival of cancer cells." (PMID 32164629, 2020). "Continuous explore about the complex mechanisms of NHERF1 regulating functions in cancers will supply more evidence to address the remaining questions." (PMID 32164629, 2020). "We found that the translocation of NHERF1 happened to heparin-induced endogenous NHERF1 expression in ALK positive cancer cells." (PMID 32164629, 2020). "NHERF1 is known to interact with a variety of proteins of great importance in human cancers, including platelet-derived growth factor receptor (PDGFR) and phosphatase and tensin homolog (PTEN)." (PMID 32164629, 2020). "The ability of E6 proteins to degrade NHERF1 augments the canonical Wnt/β-catenin signaling, an oncogenic pathway frequently active in cancer." (PMID 31002735, 2019). "There are numerous papers regarding NHERF1 human cancer phenotypes, but they are collectively inconsistent." (PMID 31002735, 2019).
cancer (continued). "Taken together, these data show that PKCz ameliorates the effects of centrosome amplification via ezrin/NHERF1 interactions, interphase centrosome clustering at the ezrin cap, and suppression of multipolar spindle formation in cancer cells." (PMID 29520890, 2018). "In the cancer model, acute perturbation of the ezrin/NHERF1 interaction had greater effects on nuclear roundness scores and nuclear area, possibly in association with intrinsic unidentified mutations." (PMID 29520890, 2018). "Here, we investigated ezrin/NHERF1 interactive effects on spindle dynamics and multicellular assembly in physiological and cancer models." (PMID 29520890, 2018). "The up-regulation of NHERF1 exposed to hypoxia was also inhibited by the anti-VEGF/VEGFR drugs in cancer cells." (PMID 27999191, 2017). "NHERF1 expression was higher in the nucleus of cancer cells than in contiguous non- mammary epithelial cells." (PMID 27097111, 2016). "In aCPP1, NHERF1 IHC showed cytoplasmic staining, similarly to CP carcinoma, and in aCPP2, apical plasma membrane staining in the papillary areas, and rings and microlumens, in the areas of compact growth." (PMID 27229317, 2016). "NHERF1 alterations are correlated with the progression and invasiveness of human tumors, and its heterogeneous distribution is a common oncogenic event in carcinomas." (PMID 27097111, 2016). "NHERF1 is a PDZ adaptor protein that scaffolds the assembly of diverse signaling complexes and has been implicated in many cancers." (PMID 24339979, 2013). "NHERF1 also plays a significant role in multiple cancers where its elevated expression correlates with aggressive stage and poor overall prognosis." (PMID 24339979, 2013). "In addition, in vitro studies have demonstrated that NHERF1 knockdown is associated with enhanced metalloproteinase 2 (MMP-2) activity, thus further supporting a role for NHERF1 in cancer invasion." (PMID 35223518, 2022). "The results partially explained why malignant cancer cells not only sustained high NHERF1 expression but also might benefit from the outcome for proliferation preference." (PMID 32164629, 2020). "Recent studies showed that the cellular distribution of NHERF1 was significantly different in cancers from normal tissues of same origins, where NHERF1 protein might shifted from the plasma membrane to the cytoplasm or nucleus." (PMID 32164629, 2020). "However, the mechanism of NHERF1 up-regulation in cancers and the contribution of NHERF1 to the regulation in the metastatic progression were still unclear." (PMID 27999191, 2017). "The most extensive analyses of the role of NHERF1 in cancer development have been performed for BC." (PMID 29029467, 2017). "The adaptor protein NHERF1 (Na/H exchanger-3 regulatory factor-1) and its associated ezrin-radixin-moesin-merlin/neurofibromin-2 (ERM-NF2) family proteins are required for epithelial morphogenesis and have been implicated in cancer progression." (PMID 27229317, 2016). "Given that PTEN-PI3K-Akt is one of the most prominent pathways relevant to tumorigenesis and targeted therapy of almost all types of carcinoma, studies on NHERF1 should be instrumental to the development of new strategies to overcome chemo-resistance and enhance efficacy." (PMID 18190691, 2008). "The diminished life span of NHERF1 null mice could limit observation of cancer traits." (PMID 31002735, 2019). "Similarly, SLC9A3R1, also known as ERM binding protein 50 (EBP50) or NHERF1 (Na+/H+ exchange regulatory factor) is a PDZ-domain containing scaffolding protein that is implicated in cancer, cell polarity and actin regulation." (PMID 30048510, 2018). "Cholesterol has also been found to bind to the PDZ domain of NHERF1/EBP50, a key contributor to the PI3K/Akt and Wnt/B-catenin pathways, thereby promoting the development of cancer." (PMID 38612893, 2024).